TGFB1 (transforming growth factor beta 1)
Diseases named in the same sentence as TGFB1 in open-access papers (continued):
Sharing a sentence is not in itself a finding about the gene and the disease.
melanoma (678 papers, 2006 to 2026). A malignant, usually aggressive tumor composed of atypical, neoplastic melanocytes. "Specifically, TGFβ-1 expression by breast cancer and melanoma cells has been reported and linked to EndMT." (PMID 37190188, 2023). "Both cancer cells and tumour-associated cells secrete VEGF and TGFβ-1 to facilitate melanoma migration." (PMID 33139674, 2020). "They express transforming growth factor β receptor 1 (TGFβR1), and are therefore susceptible to TGFβ1 and TGFβ2 specifically expressed by primary melanoma." (PMID 17565341, 2007). "The expression level of TGFB1 was associated with melanoma immune response." (PMID 35012443, 2022). "Compared with exosomes derived from benign ovarian lesions, exosomes from ovarian cancer contain significantly increased levels of TGFβ1 and melanoma-associated antigens MAGE3 and MAGE6, suggesting potential biomarkers for distinguishing malignancy from benignity." (PMID 34073560, 2021). "However, we only observed a weak, negative correlation (-0.119) between TGFB1 and non-synonymous mutation frequency across the melanoma set, and found that TGFB1 expression levels actually provided additional prognostic value beyond mutation frequency." (PMID 28448494, 2017). "To determine if our model CAFs displayed reported transcriptional changes, we analysed the expression of four genes that are controlled by the TGFβ1 signalling cascade and upregulated in melanoma CAFs." (PMID 40654904, 2025). "Here, we report that TGFB1 is expressed at high levels in all the melanoma cell lines assessed, and SRA737 + LDHU treatment triggered a modest increase." (PMID 40507298, 2025). "In the xenograft setup, the MEKi-resistant melanoma cell line was injected subcutaneously, and tumors were allowed to grow to approximately 300 mm3 before initiating three intra-tumoral injections of TGFβ1 mRNA along with daily oral MEKi treatment." (PMID 39709491, 2024). "These regions were identified in A375 melanoma cells stimulated with TGFB1 and were bound by SMAD2/3 upon stimulus." (PMID 38874379, 2024). "We found that TGFβ1 significantly reduced melanoma tumorsphere formation at picomolar concentrations in all cell lines tested except WM278 and 1205Lu." (PMID 38201651, 2024). "This, together with the finding that intra-tumoral injection of synthetic TGFB1 mRNA sensitizes human melanoma to targeted therapy in vivo, demonstrates the potential therapeutic relevance of our study." (PMID 39709491, 2024). "A human melanoma enhancer, induced upon TGFB1 signaling was identified, and stable transgenic zebrafish with this enhancer driving EGFP were generated (TIE:EGFP)." (PMID 38874379, 2024). "The full lists of genes from these Venn diagram intersections of interest encompassed a total of 42 genes, which we defined as a novel apoptosis gene signature related to combinatorial TGFβ1 + MEKi treatment in melanoma." (PMID 39709491, 2024). "Increased TGFβ1 signaling-associated downstream target genes such as TGFB1 and INHBA were observed in PGC1α silenced melanoma and lung adenocarcinoma cells." (PMID 35897813, 2022). "For example, studies on Fresolizumab, a fully human monoclonal IgG4 antibody that neutralizes mature TGFB1, were conducted for malignant pleural mesothelioma, melanoma and renal cell carcinoma." (PMID 35311155, 2022). "High-glycolysis melanoma cells upregulates TGFB1 expression thus increasing the secretion of TGF-β which inhibit mTOR signaling pathway and result in less production of IFN-γ and impaired anti-tumor function." (PMID 36003368, 2022). "The TGFβ signature of CT26 colon carcinoma is defined by TGFβ1 and TGFβ1 inhibition results in tumor delay; B16 melanoma has equal expression of both isoforms and inhibition of either TGFβ1 or TGFβ3 controls tumor growth." (PMID 34789823, 2021). "We examined and compared serum levels of both TGFβ1 and 2 in the same healthy, melanoma and lupus cohorts." (PMID 35069536, 2021).
melanoma (continued). "BRAF inhibitor vemurafenib-treated melanoma cells was found to lead to transforming growth factor beta 1 (TGF-β1) release, which increases the deposition of fibronectin, type I collagen, α-smooth muscle actin ‘as well as CAFs." (PMID 34371697, 2021). "For example, TGFβ1 protects colon cancer cells from apoptosis and TGFβ downregulation induced cancer cell apoptosis in melanoma and pancreas adenocarcinoma." (PMID 34527666, 2021). "Our study confirmed significantly higher serum levels of both TGFβ1 and TGFβ2 within the melanoma patient cohort, while analysis of lupus patient sera from a previous study identified high levels of TGFβ1 but little TGFβ2 compared with healthy donor sera." (PMID 35069536, 2021). "Serum levels of TGFβ1 were significantly raised in both the melanoma and lupus patient serum cohorts compared with healthy donors, but TGFβ2 serum levels were significantly higher solely in the melanoma patient cohort." (PMID 35069536, 2021). "Compared to the controls, we observed a significant enrichment in the immunoprecipitation of BORIS in the TGFB1 gene in both melanoma cell lines, demonstrating that BORIS physically binds the in silico identified binding site." (PMID 32123577, 2020). "There was evidence of TGFβ-1 transcripts in the melanoma cells; where these counts were lower than those detected for VEGF and osteopontin." (PMID 33139674, 2020). "We set up an overnight co-culture with melanoma cells in the presence of soluble TGFβ (1.25 ng/ml) and measured IL-2 secretion in the supernatant by ELISA." (PMID 31500665, 2019). "Treatment of CD271low melanoma cell lines with TGFβ1 at different time points led to an increase in CD271 expression at both messenger RNA (mRNA) and protein levels in different cell lines." (PMID 29215016, 2017). "Elevated TGFβ1 plasma levels have been shown to correlate with melanoma metastatic progression whereby, this cytokine is known to promote tumor progression." (PMID 29100268, 2017). "Melanoma cells can secrete high amounts of TGFβ1, inducing its own expression through a positive feedback loop." (PMID 29100268, 2017). "In vitro experiments indicated that brain-derived soluble factors and transforming growth factor β1 (TGFβ1) up-regulated ANGPTL4 expression by melanoma cells." (PMID 29100268, 2017). "In this study we investigated the potential of targeting TGFβ1 as second-line therapy for advanced melanoma." (PMID 27835901, 2016). "With specific regard to tumor-derived TGFβ1, recent work from our laboratory has shown that TGFβ1 in melanoma tumor-conditioned media also alters the maturation and activation of fully-differentiated tissue-resident DC." (PMID 27589814, 2016). "Such an approach has been implemented successfully in the B16 melanoma model, as administration of TGFβ1 siRNA in conjunction with a DC vaccine significantly enhanced the control of this tumor and was associated with a decrease in Tregs at the tumor site." (PMID 27589814, 2016). "Previous studies revealed that the BRAF mutation hyper-activated the MAPK signaling pathway and led to MITF promotion, whereas TGFB1 was reported to be down-regulated in multiple cancers, including melanoma." (PMID 25890285, 2015). "It is therefore possible that melanoma-derived TGFβ1 suppresses CD8+ T cell effector function, leading to tumor immune escape and enhanced outgrowth." (PMID 26441959, 2015). "Transforming growth factor-beta 1 (TGF-β1) was detected in the spent medium of all 25 of the melanoma cell lines and also was statistically significant in the IHC intensity comparison of primary lesions versus metastases." (PMID 24281094, 2010). "With the local administration of TGFβ1 mRNA through intra-tumoral injections, we provide a proof-of-principle that mRNA injection could be used in clinical applications to treat melanoma." (PMID 39709491, 2024). "Likewise, apoptosis can be triggered by combinatorial TGFβ1 + MEKi treatment in MEKi-sensitive as well as MEKi-resistant human melanoma cells." (PMID 39709491, 2024).
melanoma (continued). "Indeed, we found that the PI3Ki was able to block the increase in primed state cells seen when we treat with TGFB1 alone, suggesting that the TGFB1-mediated effects on priming melanoma cells is dependent on downstream PI3K activity." (PMID 37932277, 2023). "To test the hypothesis that TGFB1 induces the primed state, we treated melanoma cell lines, including WM989 and WM983B, with recombinant TGFB1 for 5 days and then performed flow cytometry for primed cell marker gene NT5E." (PMID 37932277, 2023). "Similarly, treating WM164 with a BRAF inhibitor in the presence of recombinant TGFβ1 (200 pg/mL) improved colony formation of the melanoma cells, despite the BRAF inhibitor, indicating the role of TGFβ1 in drug resistance." (PMID 36980770, 2023). "It is interesting to note that in this model of B16 melanoma, isoform-specific inhibition with anti-TGFβ1 therapy and anti-PD-1 is superior to anti-PD-1 alone; however, TGFβ inhibition in combination with anti-CTLA-4 therapy did not produce synergistic effects." (PMID 34789823, 2021). "Knockdown of LTBP4 increased the percentage of active TGFβ1 secreted by melanoma cells." (PMID 35252214, 2021). "Possibly related to its capacity to disrupt the integrity of the BBB, we found that ANGPTL4, a marker of human melanoma brain metastasis whose expression is regulated by TGFβ1,177 promotes the malignancy of cutaneous melanoma cells and augments their potential to form brain metastasis." (PMID 32761606, 2021). "Therefore, NanoString nCounter gene expression assay (detailed in the Methods section) was used to detect TGFβ-1 transcripts in cultured melanoma cells instead." (PMID 33139674, 2020). "Moreover, TGFβ-1, amongst other serum factors, can also influence the release of IL-8 in melanoma via the transcription factor NFκB." (PMID 33139674, 2020). "Interestingly, among the putative direct BORIS targets we observed TGF-beta (TGFB1), which is a well-known inducer of melanoma cell phenotype switching." (PMID 32123577, 2020). "It was fully expected that TGFβ-1 would be expressed by the melanoma lines." (PMID 33139674, 2020). "The response to TGFβ-1 is quite distinct to that observed with the melanoma conditioned media." (PMID 33139674, 2020). "Moreover, we found that alterations to cytokine/chemokine expression profiles by DC in these systems also correlated with melanoma tumorigenicity and were partially driven by tumor-derived TGFβ1 and VEGF-A." (PMID 29209327, 2017). "Given the positive correlation between TGFB1 and T cell genes in human melanomas, we hypothesized T cells might be responsible for the beneficial overall survival observed in TGFB1high patients." (PMID 28448494, 2017). "This phenotype could be partially reversed by Tgfb1 gene silencing in melanoma cells prior to ex vivo culture of tissue-derived DC in tumor-conditioned media." (PMID 27589814, 2016). "Melanoma cells engineered to over-express TGFβ1 have increased tumour forming ability." (PMID 27835901, 2016). "Interestingly, some other factors, as the MGAT5, MCAM and TGFβ1, cooperating in the induction of prometastatic phenotypes in melanoma, were induced by miR-222." (PMID 26912358, 2016). "This study revealed a key regulatory mechanism in melanoma, where BRAFV600E may play dual roles as a positive regulator of the MITF pathway and as a negative regulator of the TGFB1 pathway in the initiation of melanoma development." (PMID 25890285, 2015). "In addition, dasatinib has been reported to inhibit migration of melanoma and sarcoma cell lines, and treatment of A549 cells with dasatinib resulted in inhibition of TGFβ-1-induced migration." (PMID 25501935, 2014). "With the observed effect of boosted apoptosis in the combination treatment with TGFβ1 + MEKi, we create a context, in which the outcome of TGFβ signaling is drastically rewired from increasing invasiveness to promoting apoptosis, even in MEKi-resistant melanoma cells." (PMID 39709491, 2024).
melanoma (continued). "Therefore, TGFβ-1 expression was also assessed in the melanoma conditioned media." (PMID 33139674, 2020). "Additionally, Treg expansion in melanoma can also be driven by TGFβ1-producing regulatory DC." (PMID 29209327, 2017). "This suggests that TGFβ2 (produced either directly by melanoma or by associated fibroblasts) and not TGFβ1 might in fact be the primary melanoma-derived immunosuppressive factor." (PMID 17565341, 2007). "Together, these data demonstrate that TGFβ1‐treatment of primary NDFs generates CAF‐like cells that display biochemical and phenotypic parameters consistent with melanoma CAFs." (PMID 41179923, 2025). "Together, these data demonstrate that TGFβ1-treatment of primary NDFs generate CAF-like cells that display biochemical and phenotypic parameters consistent with melanoma CAFs." (PMID 40654904, 2025). "Consistent with the phenotype of CD163+ TAMs in the melanoma TME, moTAMs expressed the genes involved in immune suppression, including CD274 (PD-L1), PDCD1LG2 (PD-L2), and TGFB1." (PMID 38903497, 2024). "This process appears to be reverted upon MAPK pathway inhibition in the presence of TGFβ1, resulting in elevated BCL2L11 protein levels and, consequently, apoptosis induction in melanoma." (PMID 39709491, 2024). "We found that immediate-early TGFb target genes, identified following an acute 2 hr TGFB1 treatment in zebrafish melanoma cells, ZMEL1, were down-regulated in TIE:EGFPhigh cells." (PMID 38874379, 2024). "Given that VEGFA, TGFβ1, CCL5 and CXCL2 are released in cell media (CM) as soluble factors, we collected the supernatants from drug resistant A375 and M14 melanoma cells and from their sensitive counterparts." (PMID 36418472, 2023). "Gene set enrichment analysis of YY1 knockdown melanoma cells revealed Signal Transduction_TGF-beta, GDF and Activin signaling, as one of the top upregulated pathways, which encompassed the genes TGFB1, TGFBRI and TGFBRII." (PMID 35693944, 2022). "Our GSEA of siYY1-treated human melanoma cells revealed members of the TGF-β family, in particular TGFB1, among the most upregulated differentially expressed genes." (PMID 35693944, 2022). "The greatest level of B16 melanoma direct killing was seen in CD8+ T cells from animals treated with anti-TGFβ3 (47.8% killing), followed by those treated with anti-TGFβ1 (34.1% killing) and 1D11 (21.8% killing) compared to 10.6% killing in untreated controls." (PMID 34789823, 2021). "Using B16 mouse melanoma and CT26 colon carcinoma as models of stroma-poor tumors, we demonstrate that myeloid/dendritic cells are the main sources of TGFβ1 and TGFβ3." (PMID 34789823, 2021). "Gene expression comparisons between pre- and on-treatment melanoma patient samples showed a significant overall increase in IL17RA, TGFB1, and CCR5 when patients received anti-PD-1." (PMID 33972557, 2021). "We focused our validation experiments of the in silico determined BORIS target genes on TGFB1, since TGF-beta driven signaling is an important mark of the invasive signature and TGF-beta acts as tumor promoter at later stages of melanoma tumor development." (PMID 32123577, 2020). "Having identified TGFB1 as a putative direct BORIS target gene, we set out to validate the in silico analysis in melanoma cells." (PMID 32123577, 2020). "Efficacy of TGFβ1-selective inhibition in combination with anti-PD-1 was assessed in the MBT-2 bladder cancer and CloudmanS91 melanoma models." (PMID 30400822, 2018). "Based on the fact that TGFβ1 improves peritumoral angiogenesis in melanomas 14 and acts indirectly as a potent chemoattractant for monocytes/macrophages 15, which releases VEGF in response of TGFβ1 30, we investigated TGFβ1 protein levels in tumors." (PMID 24421272, 2014). "Overnight treatment of melanoma cells with AZD6244–TRAIL led to a more pronounced suppression of VEGFα and TGFβ1 secretion, compared with the effects induced by AZD6244 alone." (PMID 25275595, 2014).
melanoma (continued). "The only other report of EGF and TGFβ1 effects on ILK expression, showed stimulation of ILK expression in a human melanoma cell line following exposure to EGF and TGFβ1 for 24 and 48 hours." (PMID 16643659, 2006). "Moreover, in line with a previous study identifying Twist Family BHLH Transcription Factor 1 (TWIST1) as an anti-apoptotic modulator in melanoma, we observed downregulation of TWIST1 upon combined treatment with TGFβ1 and MEKi." (PMID 39709491, 2024). "A screening of secreted biomarkers during macrophage/melanoma interactions revealed activin A as a highly secreted factor, but not TGFβ1-2-3." (PMID 38891107, 2024). "In melanoma, CCR5/CCL5 recruits Tregs with high TGFβ1 expression." (PMID 38937380, 2024). "As reported in the literature, the mRNA transcript for TGFβ-2 is characteristic only for melanoma cells, while the transcripts for TGFβ-1 and TGFβ-3 - for normal and neoplastic cells." (PMID 36899279, 2023). "Interestingly, our study demonstrated a reduced expression of TGFB1, TFGBR1 and SMAD2 in PRELPhigh vs PRELPlow melanoma cells." (PMID 37730606, 2023). "Pericytes could increase adenosine, nitric oxide, IL-10, TGF-β1 (Transforming growth factor beta 1), and MHC-II (Major histocompatibility complex-II) levels, which participated in melanoma cell extravasation." (PMID 35574466, 2022). "In this study, we characterized the immune cell expression of TGFβ1 and TGFβ3 in non-stromal rich tumors using mouse melanoma and colon carcinoma as model systems." (PMID 34789823, 2021). "Furthermore, BORIS’ ability to bind near the TGFB1 promoter, which coincides with the upregulation of TGFB1 and TGF-beta target genes, indicates a direct role for BORIS in melanoma phenotype switching." (PMID 32123577, 2020). "Oleocanthal, oleacein and hydroxytyrosol were observed to exhibit an inhibitory effect on ERK1/2 phosphorylation in a TGFβ1-treated mesothelial cell line, non-melanoma skin cancer cell line, myeloma-derived cell line and human melanoma cell line." (PMID 31315241, 2019). "Moreover, DNMT3A, which also acts as a potential TGFB1 target, was found to be likely to mediate BRAFV600E epigenetic modifications in this study, thus facilitating melanoma development." (PMID 25890285, 2015). "Similarly, transforming growth factor beta 1 (TGF-β1) induced self-aggregation of TPC6A and Ser35-phosphorylated TPC6A, and the aggregation exhibited in a ladder-like pattern in melanoma B16F10 cells." (PMID 27551439, 2015). "We found that the CTGF overexpression is not induced by members of the TGFβ superfamiliy and its regulators in melanoma cell lines: Neither TGFβ1, BMP4 nor BMP7 have a significant effect on the CTGF expression." (PMID 21673687, 2011). "Neither treatment of melanoma cells with TGFβ1 nor transfection of Mel Im cells with an antisense Sno construct influence CTGF mRNA expression." (PMID 21673687, 2011). "As TGFβ1, BMP4 and BMP7 are upregulated in melanoma, we were interested whether CTGF expression in the melanoma cells is mediated by these cytokines." (PMID 21673687, 2011). "Transforming growth factor beta-1 (TGF-β1)selectively induces IL-8 expression in highly metastatic A375SM melanoma cells, but not in A375P non-metastatic parental cells." (PMID 24281035, 2010). "Strikingly, the expression of TGFβ1 was not increased further once melanoma progressed into the lymph nodes, suggesting that the negative SLN is already immunosuppressed prior to melanoma metastasis." (PMID 17565341, 2007). "In primary melanoma, TGFβ2 is likely to render peripheral DCs tolerogenic, while in lymph nodes IDO and TGFβ1 may have a major effect." (PMID 17565341, 2007). "These could then migrate to the SLN, before any tumour spread takes place and prime the site for tumour growth, by producing IDO and TGFβ1, and making the SLN an immunoprivileged site suitable for melanoma metastasis." (PMID 17565341, 2007).